TNF (tumor necrosis factor)
Diseases named in the same sentence as TNF in open-access papers (continued):
Sharing a sentence is not in itself a finding about the gene and the disease.
COVID-19 (continued). "High plasma levels of pro-inflammatory cytokines (interleukin-2, interleukin-7, granulocyte colony-stimulating factor, IP10, MCP1, MIP1A and tumor necrosis factor-α) have been observed in critically ill COVID-19 patients admitted to intensive care units." (PMID 33752721, 2021). "International registries of patients with IMIDs have provided initial information regarding COVID-19 outcomes among individuals who received TNF inhibitor therapies during the pandemic." (PMID 34661663, 2021). "Patients with moderate COVID-19 disease had elevated levels of TNFα and IL-6, and in severe COVID-19 cases the production of IL-6 and TNF-α and other cytokines was profoundly increased." (PMID 33465050, 2021). "The lower odds of unfavorable COVID-19 outcomes among patients receiving TNF inhibitors before SARS-CoV-2 infection has several possible explanations." (PMID 34661663, 2021). "Regarding TNF-α, the proposition that anti-TNF therapy should be initiated at the early and middle stages in patients with COVID-19 to prevent progression has been refuted." (PMID 33404925, 2021). "Increased expression of the cytokines IL-6, IL-10, and TNF-α is closely related with severe COVID-19." (PMID 34484133, 2021). "Logistic regression analysis revealed that TNF-α independently discriminate disease severity in COVID-19 patients." (PMID 34150910, 2021). "A randomized controlled trail to evaluate adalimumab, an anti-TNF agent, for COVID-19 treatment has been registered (ChiCRT2000030089)." (PMID 34725309, 2021). "This process is mediated by tumour necrosis factor-alpha (TNFα) and interleukin 6 activity.Many reports also highlighted a strong association between elevated PCT and severe COVID-19." (PMID 34855832, 2021). "It was reported that plasma cytokines IFN-γ, IL-10, IL-12p70, IL17A, IL-6 and TNF-α levels are increased in COVID-19 patients admitted to the ICU when compared with healthy controls." (PMID 34289718, 2021). "Another study confirmed severe COVID-19 patients correlated with increased TNF-α as well as IL-4, where TNF-α was associated with lymphocyte apoptosis and IL-4 interfered with T regulatory cell activity." (PMID 34199761, 2021). "In stroke patients with COVID-19, the cytokines IL-1β, IL-6, and TNF-α are representative as well as in the CSF and blood serum." (PMID 34577633, 2021). "Now coming to the continuation of bDMARDs in rheumatic patients in COVID-19 condition, anti-TNF therapy has been found to lower the disease severity and mortality." (PMID 34943795, 2021). "Our results revealed a stronger positive correlation between serum values of IL-33 and innate immunity mediators TNF-α, IL-1β, IL-6, IL-12, and IL-23 in the severe form of COVID-19." (PMID 34917631, 2021). "Research has been emphasizing how targeting TNF-α is important for a better prognosis against COVID-19-induced cytokine dysfunction, once its blockade can reduce both inflammatory and prothrombotic biomarkers." (PMID 33968948, 2021). "MIS-A patient PBMC responses to SARS-CoV-2 were largely similar to those of PBMCs from ICU patients with severe COVID-19, however IFNγ, TNFα; and IL-1β responses tended to be higher in MIS-A PBMCs although not significantly across all cases." (PMID 34531865, 2021). "It is important to underline that TNF α and IL6, which are increased in IBD patients, have been also associated with severe forms of COVID-19." (PMID 34572185, 2021). "We also assessed plasma levels of three major proinflammatory cytokines, IL-1β, IL-6 and TNFα, and IL-10, an anti-inflammatory cytokine, in COVID-19-naive older adults." (PMID 34868051, 2021). "We determined serum TNF-α and sTNFR1 concentrations in 46 patients with laboratory-confirmed COVID-19 (17 patients with severe disease within the intensive care unit [ICU] and 29 non-severe, non-ICU patients) and 15 healthy controls upon admission using ELISA." (PMID 33968010, 2021).
COVID-19 (continued). "Significantly higher levels of galectin-3, galectin-9, IL-1β, IL-1Ra, IL-10, IFN-α2, IL-6, IL-18, and TNF-α were observed in severe COVID-19 and active AOSD patients compared with HC (all p<0.001)." (PMID 34367188, 2021). "For SARS-CoV-2, higher serum levels of TNF-α have been observed in many patients with severe COVID-19 compared with individuals with mild disease." (PMID 34938746, 2021). "In our study, in both of the COVID-19 groups of patients IL-2 was at the lowest level, TNFα was only slightly elevated, while INFγ was significantly higher in the non-ICU COVID-19 patients." (PMID 34071149, 2021). "The activation of this pathway results in the release of pro-inflammatory cytokines including IL-6 and TNF-α, which are vastly elevated ones in severe COVID-19 patients." (PMID 35401158, 2021). "Of these age-correlated proteins, six had been also associated with COVID-19 severity: HGF and CXCL9 shown the highest coefficients while IL10RB, VEGFA, IL-6 and TNF showed low albeit significant correlation (r < 0.30)." (PMID 34335580, 2021). "Compared with that in the non-COVID-19 group, the levels of Interleukin-2 (IL-2), Interleukin-6 (IL-6), Interferon-gamma (IFN-γ) and tumor necrosis factor-alpha (TNF-α) were significantly increased in the COVID-19 group (P < 0.05)." (PMID 35071136, 2021). "The limited data suggests that COVID-19 pregnancies have similar elevations of cytokines (IL-6, TNFα) and chemokines (CCL2, CXCL10) as other COVID-19 patients." (PMID 33168125, 2021). "Initially, we observed that SARS-CoV-2-specific memory CD4+ and CD8+ secreted low levels of IFNγ and only a small proportion of the T cells from COVID-19 patients gained multifunctionality (IFNγ and TNF dual expression)." (PMID 33741972, 2021). "A study found that TNF-α and IFN-γ synergism mediated RIPK1/FADD/CASP8 axis-derived PANoptosis in murine bone marrow-derived macrophages (BMDMs) drives pathology in COVID-19 and other diseases associated with cytokine storm." (PMID 34594225, 2021). "Many proinflammation cytokines, including IL-2, IL-6, IL-7, IL-10, granulocyte colony stimulating factor (GCSF) and TNF-α, were significantly increased in the periphery of severe COVID-19 patients." (PMID 33912590, 2021). "Our multivariate model showed that COVID-19 was related to increased expression levels of TNF-α, IL-1β, IL-6, IL-8, IL-12B, and IL-10 (P < 0.05), and that leprosy simultaneously enhanced the levels of IL-6 (P = 0.046) and IL-12B (P = 0.020)." (PMID 33819170, 2021). "Among these cytokines, serum levels of IL1-β, IL-6, IL-8, and TNF-α were found to be significantly increased in the critical COVID-19 patients relative to mild patients." (PMID 34276659, 2021). "Multivariate logistic regression analysis was performed to ascertain the effects of age, IL-6, and TNF-α levels on the likelihood that participants had COVID-19." (PMID 34578450, 2021). "Compared to those alive, all the patients who died from COVID-19 had increased levels of TNF-α, IL-2R, IL-6, IL-8, and IL-10 tested on admission." (PMID 33735106, 2021). "Immunofluorescent staining further revealed that IFN-γ was co-localized with the maternal blood in the placentas, but TNF-α was primarily co-localized with placental trophoblast cells in the COVID-19 group." (PMID 35071136, 2021). "In turn, sleep deprivation has been shown to affect the immune system, increasing interleukins (IL-6, IL-17) and tumor necrosis factor-a (TNF-a), promoting inflammation and possibly exacerbating the cytokine storm in COVID-19, which is related to ARDS." (PMID 34834555, 2021). "In severe COVID-19 lung macrophages displayed high expression of IL-1β, IL-6, TNF-α and various chemokines (CCL2, CCL3, CCL4, CCL7, CXCL9, CXCL10 and CXCL11)." (PMID 34054832, 2021). "The SARS-CoV-2 induced COVID-19 evoked overexpression of pro-inflammatory cytokines such as IL-6 and TNF-α, which are products of the TLR-4 pathway." (PMID 34200327, 2021).
COVID-19 (continued). "High expression of Tumor Necrosis Factor (TNF) has been widely reported in patients with COVID-19, where increased levels of this pro-inflammatory cytokine promotes intestinal epithelial barrier permeability." (PMID 34161337, 2021). "Increased levels of cytokines often occur in critically ill patients with COVID-19, including IL-6, IL-2R, IL-10, and tumor necrosis factor-α." (PMID 34858386, 2021). "Although plasma levels of TNF-α remained low in COVID-19 patients, TNF-α levels were significantly higher in the severe COVID-19 group compared with healthy donors." (PMID 33986193, 2021). "COVID-19 patients have higher serum levels of IL-6, IL-1β, soluble IL-2 R, IL-8, IL-10, IL-17, and TNF-α." (PMID 33757410, 2021). "IL-1β and TNF-α, two cytokines elevated in cytokine release syndrome in COVID-19 patients, decreased KLF2 gene expression." (PMID 34253708, 2021). "Secondly, we demonstrated profound dysfunction of T lymphocytes and NK cells in critically ill COVID-19 patients with diminished secretion of key cytokines such as IL-2, INFγ, and TNFα." (PMID 34071149, 2021). "Kaplan-Meier survival curves showed that higher IL-2R, IL-6, IL-8, IL-10, and TNF-α levels were significantly correlated with reduced survival time in COVID-19 (all P < 0.001)." (PMID 33542929, 2021). "MAIT cells of COVID-19 patients also had lower expression levels of TNF-alpha, perforin and granzyme B upon stimulation with IL-12 + IL-18." (PMID 34238985, 2021). "Production of proinflammatory cytokines (IL-1β, IL-6, and TNF-α) fundamental in COVID-19 pathology can directly affect platelet function and further contribute to their prothrombotic tendency, even leading to their exhaustion." (PMID 33670394, 2021). "In patients with severe COVID-19, a decrease in lymphocytes count was negatively correlated to the serum inflammatory cytokines levels (IL-6, TNF)." (PMID 34952570, 2021). "Compared with a severe influenza group, PBMCs from COVID-19 patients showed a high inflammatory response, and a marked TNF/IL-1β driven inflammatory response." (PMID 34746034, 2021). "Inflammatory cytokines IL1β, IL6, IL8, and TNFα increased in the plasma of moderate and severe COVID-19 patients." (PMID 33767630, 2021). "Specifically, Lee and colleagues reported that type I interferon and tumor necrosis factor alpha (TNF-α)/IL-1β correlated with COVID-19 severity." (PMID 34319784, 2021). "In COVID-19 patients, the pro-inflammatory cytokines like IL-1, IL-2, IL-6, IL-7, IL-10, IP-10, and TNFα as well as chemokines like IL-8 are found in higher concentrations." (PMID 33981235, 2021). "It has further been reported that TNF-α serum levels are increased in COVID-19 patients with higher levels detected in severe cases." (PMID 34276659, 2021). "Most importantly, high plasma levels of PTX3, MCP1, and TNFα in COVID-19 patients have been described as early molecular indicators of adverse disease progression needing intensive care." (PMID 33399033, 2021). "The T lymphocytes and natural killer (NK) cells profiles were described, assessing the levels of IL-2, TNFα, and INFγ in the peripheral blood in both of the studied groups of patients with COVID-19." (PMID 34071149, 2021). "Lymphocyte count was negatively associated with IFNγ, IL-2, TNFα, IL-1α, IFNβ, IL-6, IL-17A, IL-10, CXCL-10 and VEGF in children with PIMS-TS and COVID-19." (PMID 33813138, 2021). "The ‘cytokine storm’ of proinflammatory cytokines such as IL-6 and TNF-αobserved in COVID-19, in addition to amyloid beta (Aβ) and phosphorylated tau, resembleprocesses of the pathogenesis of Alzheimer’s disease and inflammatory response observedpost-surgery." (PMID 34222864, 2021). "Elevated levels of infection-related biomarkers (ESR, IL2R, IL6, IP10, PCT, SF, CRP, TNFα) were detected in many patients with severe COVID-19." (PMID 33542448, 2021).
COVID-19 (continued). "In this article, we will review the drugs that have indication in patients with COVID-19, including corticosteroids, antimalarials, anti-TNF, anti-IL-1, anti-IL-6, baricitinib, intravenous immunoglobulins, and colchicine." (PMID 33669218, 2021). "Cytokine profiles in COVID-19 patients have revealed increased levels of interleukin-1β (IL-1β), IL-2, IL-6 and tumor necrosis factor-alpha (TNFα)." (PMID 33927728, 2021). "Many inflammatory cytokines (Interferon-alpha (IFN-α), interleukin-1beta (IL-1β), interleukin 6 (IL6), interleukin 12 (IL-12), tumor necrosis factor-alpha (TNF-α), and transforming growth factor-beta (TGFβ) and chemokines were detected in COVID-19 patients." (PMID 34908920, 2021). "In our study, we found that the core pathogenesis target of COVID-19 was TNF, while the secondary pathogenesis targets included IL6, IL10, and IL2 cytokines." (PMID 34731090, 2021). "In our cohort, we observed that serum levels of IL-6 and TNF-α were more elevated at diagnosis in children affected by COVID-19 compared with other infectious diseases." (PMID 34578450, 2021). "Similar to previous research, IFN-γ and TNF-α are significantly higher in COVID-19 patients than in healthy individuals." (PMID 34489974, 2021). "Systemic inflammatory cytokines such as interleukin-6 (IL-6) and tumor necrosis factor-alpha (TNF-α) and specific Th1 cytokines like interferon-induced protein-10 (IP-10) are associated with COVID-19 severity and mortality." (PMID 34938289, 2021). "Older age, underlying hypertension, high cytokine levels (interleukin [IL]-2R, IL-6, IL-10, and tumor necrosis factor [TNF]-α), and high ferritin levels are significantly associated with severe coronavirus disease 2019 (COVID-19)." (PMID 34015009, 2021). "Suppressors of cytokine storm as well as anti-inflammatory drugs must be investigated as promising treatments for COVID-19, including stem cell therapy, TNF blockers, immunosuppressants, and IL-1 antagonists." (PMID 34577633, 2021). "The importance of TNF-α in COVID-19 has been highlighted with a recent clinical trial involving Adalimumab, a TNF-α inhibitor, as a potential treatment for COVID-19 patients (CHICTR2000030089)." (PMID 34576032, 2021). "Immune dysfunction in COVID-19 patients has been attributed to pro-inflammatory cytokines including Tumor necrosis factor-α (TNF-α) and interleukin-6 (IL-6)." (PMID 35127733, 2021). "The DBN model yielded notable dependencies between TNF and IL-6, which support its robustness and generalizability since the analysis has identified both as predictors for monitoring COVID-19 patients." (PMID 35054223, 2021). "In relation to COVID-19, IL-37 has been suggested to be a potential treatment based on its anti-inflammatory profile to inhibit IL-1β, IL-6 and TNF, which are the main players of the cytokine storm." (PMID 34422917, 2021). "Rajendra supports our findings and partially share the same explanation about the molecular mechanism that TNF-α is an independent hazardous factor for COVID-19 related death and disease severity." (PMID 34725309, 2021). "Recent studies demonstrated that severe cases of COVID-19 exhibit increased plasma levels of TNF-α and IL-17 compared to mild cases." (PMID 33802569, 2021). "When we analyzed the median proportion of selected cytokines levels (pg/mL) such as: IL-1β, IL-4, IL-5, IL-6, IL-8, IL-10 and TNFα, we observed significant difference between severe COVID-19 and critical COVID-19 patient only for IL-6 level." (PMID 34064802, 2021). "Patients with mild COVID-19 showed higher TNF-α and COX-2 expression in LPS-activated monocytes compared to patients with severe disease." (PMID 34944517, 2021). "When we probed cytokine (i.e. IL-12 and IL-18)-mediated MAIT cell activation, MAIT cells from COVID-19 patients showed an altered cytokine expression profile characterised by impaired upregulation of IL-17A, TNFα, granzyme B and perforin." (PMID 33546489, 2021).
COVID-19 (continued). "Other research indicates that among patients with autoimmune diseases, those receiving disease-modifying antirheumatic drugs (DMARDs) have higher COVID-19 mortality than those treated with tumor necrosis factor inhibitors (TNFis)." (PMID 34696259, 2021). "Interferons are downstream inflammatory products of IL-1, IL-6, and tumor necrosis factor (TNF), key inflammatory molecules released by immune cells in multiple tissues affected by COVID-19." (PMID 34512253, 2021). "In other studies, while IL-6, IL-8 and TNF-α were significantly raised above their normal levels among COVID-19 ARDS patients, the increases were significantly less than in non-COVID ARDS or sepsis patients." (PMID 33672738, 2021). "COVID-19 patients have increased levels of pro-inflammatory effector cytokines, such as tumor necrosis factor alpha (TNFα), interleukin (IL)-1B, and IL-6, as well as chemokines, such as CCL2 and CXCL10, especially in those who are critically ill." (PMID 33730024, 2021). "The authors suggested that, with COVID-19, excessive production of TNF-α hinders the establishment of GC responses due to the inhibition of follicular T-cell differentiation and the induction of Th1 responses." (PMID 34830421, 2021). "While we used 225 KEGG COVID-19 pathway genes as the training set, TNF is found to be the top candidate gene." (PMID 34067609, 2021). "Hyperinflammation in COVID-19, also described as a cytokine storm, is characterized by increased proinflammatory cytokines, such as IL-6 and TNF-α." (PMID 34744508, 2021). "Chemokines such as IL-8/CXCL8 and proinflammatory cytokines such as IL-6 (p<0.05) and TNFα (p<0.05) were increased 1.4-, 4.7-, and 1.3-fold, respectively, in the plasma of patients with critical COVID-19, in comparison with patients with mild disease." (PMID 34122423, 2021). "First, we compared the prevalence, magnitude, and phenotypical profile of SARS-CoV-2–responding CD4+ T cells (e.g., cells producing IFN-γ, TNF-α, or IL-2) between hospitalized non–COVID-19 controls and confirmed COVID-19 patients." (PMID 33945513, 2021). "The areas under ROC curves (AUROCs) were 0.868 for NLR, 0.811 for IL-6, 0.802 for IL-2R, 0.763 for IL-8, 0.731 for IL-10 and 0.699 for TNF-α when performing prediction of severe or critical COVID-19 cases." (PMID 34282057, 2021). "Reduction of inflammation in HIV.High probability of survival in COVID-19.Improvement in response to Hepatitis B vaccination.Improvement in anti-cancer activity of monocytes in type 2 diabetes.↓IL-1, TNF-α in polycystic ovary syndrome." (PMID 34135894, 2021). "Based on the maximum degree value, TNF and AKT1 were respectively identified as the core targets in the network of COVID-19 pathogenic targets and the network of LHQW therapeutic targets." (PMID 34731090, 2021). "In particular, Gal-9, IL-6, IP-10, IL-10, and TNF-α were substantially higher in COVID-19 patients versus HCs." (PMID 33947753, 2021). "Recent data have shown that minocycline is an effective drug, being able to reduce COVID-19–related complications through attenuation of cytokine storm as apparent by the reduction of IL-6, IL-1, and TNF-α." (PMID 33967777, 2021). "Studies have shown that patients with severe COVID-19 characterised by a “cytokine storm” inexorably exhibit high levels of IL-6 and TNF-α in serum, and IL-6 or TNF-α antagonist seem to be very promising for severe COVID-19 cases." (PMID 34059076, 2021). "Cytokine profiles observed in COVID-19 patients have revealed increased levels of IL-1β, IL-2, IL-6, and TNF-α and increased NF-κB pathway activity." (PMID 33927728, 2021). "COVID-19 can spur glial cell activation and heightened inflammation in the CNS through the escalation of IL-6, IL-12, and IL-15, as well as tumor necrosis factor-alpha (TNF-α)." (PMID 32789802, 2021).